CXCR4 (C-X-C motif chemokine receptor 4)
Diseases named in the same sentence as CXCR4 in open-access papers (continued):
Sharing a sentence is not in itself a finding about the gene and the disease.
tumor (continued). "CXCR4 is overexpressed in many neoplasms, being capable of increasing tumor growth and invasiveness." (PMID 31620068, 2019). "Several studies have highlighted the critical role of the CXCL12–CXCR4 axis in cancer progression, and overexpression of CXCR4 by tumor cells is generally considered a poor prognostic marker." (PMID 31921208, 2019). "Our data shows this relationship between MDMX and CXCR4 only occurs in vivo, thereby suggesting signaling events regulated by a tumor stroma interaction." (PMID 31489110, 2019). "According to the defined threshold for each molecule, CXCR4-positive CTCs were identified in 90% of the patients with detectable tumor cells in their blood." (PMID 31370904, 2019). "The hijacking of the CXCL12/CXCR4 signaling pathways by tumor cells for the purposes of metastasis and protection from apoptosis rapidly identified the blockade of this axis as a potential treatment target for cancer." (PMID 31428099, 2019). "These were validated in another highly metastatic Pa03C PDAC cell line, supporting a role for stromal CXCR4 blockade in attenuating tumor progression within the neoplastic compartment." (PMID 31663852, 2019). "An expansion of CXCR4-expressing tumor cells was detected by immunohistochemistry in PD/S-SCCs, as compared to WD-SCCs." (PMID 30874597, 2019). "Compared with the tumor tissues injected with normoxic cells, tumor tissues injected with cells exposed to hypoxia displayed strong immunoreactivity of the CXCR4 expression compared with those cultured under the normoxic conditions." (PMID 30760238, 2019). "In conclusion, we demonstrate that CXCR4 signaling plays a major role in neutrophilic innate immune response to early metastatic events and contributes to the establishment of tumor micrometastases." (PMID 30787324, 2019). "Inhibition of CXCR4 or TβRII expression by shRNA in tumor cells significantly attenuated the lung metastatic index resulting from the actions of CAFs, as compared with the effect of GFP-shRNA." (PMID 31331982, 2019). "Altogether, we concluded that the medium and low cell binding antibody backbones, h17-NA and h17-NV.TS, respectively, provide anti-CXCR4 ADCs with adequate anti-tumour activity in vivo." (PMID 30792442, 2019). "Clinically, patients with cervical cancer treated with standard-of-care radio-chemotherapy and the CXCR4 inhibitor plerixafor showed improved primary tumor response and reduced metastases." (PMID 30813533, 2019). "A transcriptional study on recurrent AC disclosed the upregulation of 16 genes and a significant association of tumor relapse with the expression of CXCL12 and CXCR4." (PMID 31191748, 2019). "Membranous CXCR4 expression was widely detected on the tumour cells from control mice, whereas CXCR4 expression was reduced in tumours of ADC 713-treated mice." (PMID 30792442, 2019). "Collectively, our findings confirmed that Notch1 promotes GICs invasion self-renewal and tumor growth through the AKT/mTOR pathway mediated by CXCL12/CXCR4 axis and thus provide evidence of a promising target for GBM management." (PMID 31382985, 2019). "Stromal cell-derived factor SDF-1 and its receptor, namely CXC chemokine receptor-4 (CXCR4), are major mediators of stem cell infiltration to the tumor microenvironment." (PMID 31555593, 2019). "Neutrophils with the pro-tumor N2 phenotype possess CXCR4, VEGF, and MMP-9 markers, which facilitate tumorigenesis, promote tumor growth, stimulate angiogenesis, and mediate immunosuppression." (PMID 31681613, 2019). "C-X-C chemokine receptor type 4 (CXCR4)-expressing tumour cells migrate along the SDF-1 gradient to distant organs containing high levels of SDF-1 expression, eventually leading to metastasis." (PMID 31752959, 2019). "Our findings also suggest improved long–term tumour control with CXCR4 inhibition (43% vs. 14%), implying the potential for higher cure rates in patients." (PMID 31239542, 2019).
tumor (continued). "We previously reported that radiochemotherapy (RTCT) and concurrent administration of the CXCR4 inhibitor plerixafor improved primary tumour response." (PMID 31239542, 2019). "sh-CXCR4 tumors showed a reduced percentage of α6-integrin+/CXCR4+ tumor cells, and specifically of CXCR4-expressing CSCs, compared with sh-control tumors, whereas the percentage of CXCR7-expressing CSCs was not affected." (PMID 30874597, 2019). "[68Ga]Pentixafor is a promising ligand for imaging CXCR4 expression in multiple tumor types, but its utility is limited by the physical properties of 68Ga." (PMID 31022852, 2019). "Flow cytometry analysis showed that around 3–7% of tumor cells expressed CXCR4 (α6-integrin+/CXCR4+ cells) in WD-SCCs, and this frequency was significantly increased in PD/S-SCCs." (PMID 30874597, 2019). "At the same time, it is important to consider the effect of CXCR4 signaling on the tumor microenvironment, especially in view of the antagonizing or supportive functions that myeloid cells are known to have on tumor progression." (PMID 30787324, 2019). "In vivo, we found that losartan decreased CXCR4 levels in tumor tissues and SDF-1α at the mRNA level in lymph nodes." (PMID 31219799, 2019). "This is based on the capability of the matrix, dermal filler, plus the properties of CXCL12 to develop a suitable pre-metastatic niche with attractive capability for CXCR4 expressing circulating tumor cells." (PMID 31332163, 2019). "We investigated the role of circulating tumour cells (CTCs) and CXCR4 expression on CTCs as potential predictors of skeleton invasion." (PMID 30636773, 2019). "Up-regulation of CXCR4 and KIT is associated with leukemic blasts and PCDH10 is a common tumor suppressor that is also epigenetically silenced in hematopoietic malignancies." (PMID 30575819, 2019). "In the H929-VR20 MM model, selected in vitro as a H929 sub-population resistant to 20 nM bortezomib, CXCR4 expression is up-regulated and ADC 513 caused significant tumour growth inhibition." (PMID 30792442, 2019). "CXCL12, together with its C-X-C motif receptor 4 (CXCR4), which is overexpressed in malignant cells, plays an important role in the development of BMs, because its activation promotes tumor cell proliferation and angiogenesis." (PMID 31500357, 2019). "Meanwhile, type I IFNs from tumor trigger differentiation of neutrophils to achieve an anti-tumoral phenotype, reducing not only CXCR4 expression in neutrophils which mediates tumor-homing, but also VEGF and MMP9 expression." (PMID 31474975, 2019). "Images were analyzed visually and semi-quantitatively for CXCR4 expression including calculation of tumor-to-background ratios (TBR)." (PMID 31245296, 2019). "In HCC, CXCR4 expression has been correlated with tumor size, distant dissemination and poor prognosis of patients 20, 22, 39-41." (PMID 31534521, 2019). "There have been various reports suggesting that CXCR4 is required for tumor proliferation, invasion, angiogenesis, and modulation of the immune response." (PMID 31382985, 2019). "Our studies revealed that the blood vessels existing in OSCC stroma highly expressed CXCR4, and CXCR4 antagonism promoted tumor necrosis in OSCC." (PMID 31336612, 2019). "It is documented that CXCR4 signaling supports tumor metastasis formation in tissues where CXCL12, its cognate ligand, is abundant." (PMID 30787324, 2019). "The T47D.vector CXCR4 average mRNA level (from ten tumors) was the same as that observed for the MDA-MB-231.mir30.vector tumor samples (from six tumors)." (PMID 30642351, 2019). "U. dioica extract treatment decreased miR-21 expression, which substantially reduced the overexpressed MMP1, MMP9, MMP13, vimentin and CXCR4, and increased E-cadherin in the treated tumor cell lines." (PMID 31362429, 2019).
tumor (continued). "CXCR4 was also expressed in a subset of tumour cells from a KRASG13R mutant NSCLC patient-derived xenograft (PDX) model, featuring resistance to cisplatin and trametinib and partial resistance to paclitaxel (TM00226, The Jackson Laboratory PDX Database)." (PMID 30792442, 2019). "For example, CXCR4 is overexpressed by many tumor types, including breast, ovarian, prostate, melanoma, and neuroblastoma, among others." (PMID 31507535, 2019). "In particular, CXCL12 secreted by LECs in the LN SCS contributes to an attractive and supportive metastatic niche for CXCR4+ tumor cells." (PMID 31105685, 2019). "In conclusion, we propose that CXCR4 signaling supports the interaction between tumor cells and host neutrophils in developing tumor metastases." (PMID 30787324, 2019). "For example, the C-X-C motif chemokine receptor 4 oncogene CXCR4 can be directly targeted by tumor-suppressive miR-9, resulting in the inhibition of NPC pathogenesis." (PMID 31456943, 2019). "CXCR4 has been tied to tumor progression and poor prognosis and expression of its ligand SDF1 correlates with poor survival." (PMID 31921628, 2019). "ASCs migrate toward chemo-residual TNBC cells via SDF-1α/CXCR4 signaling, and drive chemo-residual tumor cell proliferation in a paracrine manner by secreting FGF2 and activating ERK." (PMID 30594967, 2019). "CXCR4 promotes tumor growth and malignancy, enhances tumor angiogenesis, and participates in tumor metastasis." (PMID 31744214, 2019). "SDF-1/CXCR4 signaling appears to play very important roles, since it regulates all steps in tumor progression, angiogenesis, metastasis, and survival." (PMID 30844765, 2019). "Using in vivo models and the B-ALL cell lines REH and Nalm-6, the tetraspanin CD9 was shown to modulate CXCR4-mediated cell migration involving Rac1 signaling, as well as tumor cell survival and homing into the BM and testes." (PMID 30787933, 2019). "PTCH-positive blood vessels have the potential to be a therapeutic target because CXCR4 is expressed in specific tumor blood vessels." (PMID 31744214, 2019). "Immunohistochemistry on human clinical specimens revealed that CXCR4 and a tumor vasculature marker CD34 were co-distributed in tumor vessels in human OSCC specimens." (PMID 31336612, 2019). "MMPs are well known to regulate angiogenesis and tumor invasion and metastasis while CXCR4 is involved in MSC migration and CXCR7 in MSC survival." (PMID 31013896, 2019). "Here, we address the role of the host-dependent CXCR4 signaling in driving the communication between tumor cells and neutrophils, during experimental metastasis formation in an in vivo zebrafish xenogeneic model." (PMID 30787324, 2019). "An NRF1-induced BCSC-like subset was able to form xenograft tumors in vivo, while inhibiting transcription of CXCR4 prevented xenograft tumor growth." (PMID 30486409, 2018). "Based on these findings, we conclude that CXCR4 antagonism converts cold tumors into hot tumors by facilitating the infiltration of tumor-specific effector cells into the TME." (PMID 30400835, 2018). "Homing of tumor cells to the bone marrow microenvironment, involving especially the CXCR4/SDF-1 axis, allows them to survive, proliferate and resist to therapy." (PMID 29844860, 2018). "Collectively, these data indicated that miR‐9 is a tumour suppressor and implies CXCR4 as its potential oncogene target in HNSCC." (PMID 29959873, 2018). "The blockade of the CXCR4 pathway during sorafenib treatment inhibits lung metastasis and improves the overall survival by preventing tumor vascular growth and increase of EMT markers." (PMID 30591657, 2018). "Even in the absence of applying CED, we noted moderate immunoreactivity in the tumor bulk for phosphorylated CXCR4, a known marker of CXCR4 activation and signaling." (PMID 30451884, 2018). "Targeting SDF-1, and of neutralizing CXCR4 represented a therapeutic strategy for cancer, both of which depicted a elevated expression level in many kinds of tumor cells." (PMID 30349420, 2018).
tumor (continued). "There are several studies which attempt to specifically address the role of CXCL12/CXCR4 in mediating tumor osteolysis and tumor growth within bone." (PMID 29930538, 2018). "Together, these results indicate that miR‐9 knockdown similar to CXCR4 overexpression makes cells responsive to CXCL12 and strongly suggest that miR‐9 tumour‐suppressive effects are mediated via CXCR4 pathway." (PMID 29959873, 2018). "In cancer, the physiological roles of CXCL12/CXCR4 pathway can be co-opted to promote tumor growth and metastasis." (PMID 29554149, 2018). "We assayed its selectivity and CXCR4 dependence regarding tumor tissue uptake, internalization in CXCR4‐overexpressing MetSCs (target cells), intracellular release of the cytotoxic drug FdU, and selective CXCR4+ MetSC killing." (PMID 30190334, 2018). "CXCR4 inhibition using AMD3100 to disrupt the adhesion of multiple myeloma cells to the niche mobilized the tumor cells into the circulation, where they were sensitive to anti-tumor treatments including doxorubicin and bortezomib." (PMID 29642534, 2018). "When comparing CXCR4 expression in the TMAmets, it was expressed in half of the primary tumours and one third of metastasis; it was expressed in low percentages of carcinoma cells, and no preferential expression in brain metastasis was seen." (PMID 29976164, 2018). "If desired, HuCXCR4KI can be crossed to tumor-prone genetically engineered mouse models in the same C57Bl6 background to potentially generate tumors expressing human CXCR4 in both tumor and host cells." (PMID 29554149, 2018). "The decreased trend of CXCR4 expression from PT to DM observed for the entire cohort was also maintained in the luminal A, luminal B and TN tumor subtypes." (PMID 30012106, 2018). "First, blocking the CXCR4/SDF-1 interaction would lead to egress of CXCR4-expressing tumor cells out of the tumor niche." (PMID 29844860, 2018). "Receptor CXCR4 on cancer cells at the primary tumor site responds to CXCL12/Stromal-derived factor-1α, which is secreted into circulation by osteoblasts, inducing chemotaxis and further homing to and accumulation in the bone." (PMID 29865211, 2018). "In intraperitoneal papillary epithelial ovarian cancer, CXCR4 antagonism increased tumor cell apoptosis and necrosis, reduced intraperitoneal dissemination, and selectively reduced intratumoral FoxP3 Tregs." (PMID 30622535, 2018). "Specifically, we found that targeted ablation of Cxcl12 in Il7-Cre+ stromal cells abrogates the tumor-initiating potential of BC cells and that this niche dependence can be therapeutically harnessed through antagonism of CXCR4." (PMID 29632733, 2018). "Targeting SDF-1 and neutralizing CXCR4 represented a therapeutic strategy for cancer, both of which depicted a elevated expression level in many kinds of tumor cells." (PMID 30349420, 2018). "The interaction of Stromal Cell-Derived Factor 1 (SDF1) with its receptor C-X-C Motif Chemokine Receptor 4 (CXCR4) is operative to guide the tumor cells to the peri-endothelial space." (PMID 30208949, 2018). "The angiogenesis, invasion, and tumor growth of human HCC cells are correlated with the overexpression of CXCR4 or CXCR7." (PMID 29734668, 2018). "F50067 (F50067 hz515H7-1), a humanized monoclonal IgG1 anti-CXCR4 antibody that specifically targets CXCR4, has demonstrated preclinical promising anti-tumor activity in MM." (PMID 29844860, 2018). "Higher expression levels of SDF1/CXCR4 in hepatocarcinoma cells are found compared to normal liver cells in vitro and in vivo, which favor cell proliferation and metastasis of tumor cells." (PMID 29783989, 2018). "Previously, we designed a tumor cell-targeted therapy that delivered a CXCR4 antagonist expressed in the context of the murine Fc fragment of IgG2a via an OVV (OVV-CXCR4-A-Fc)." (PMID 30149659, 2018). "CXCR4 is a chemokine receptor that recruits blood stem cells and increases tumor cell growth and invasiveness." (PMID 29515781, 2018).
tumor (continued). "Loss induces systemic autoimmunity and expansion of Foxp3+ Tregs (Treg-extrinsic mechanism).Mediates SDF1/CXCR4 axis at the tumor site (Treg-extrinsic mechanism)." (PMID 30364244, 2018). "At metastatic lesions, HER2-overexpressing tumors presented significant higher CXCR4 expression than the other tumor molecular subtype." (PMID 30012106, 2018). "The CXCR4/CXCL12 axis plays a central role in the trafficking of key immune cells in the tumor microenvironment (TME)." (PMID 30400835, 2018). "CXCR4-targeted tracer accumulation in tumor tissue is heterogeneous and seems to be, inter alia, dependent on histological subtype." (PMID 30191351, 2018). "In NPC, our previous studies showed that both miR-9 and miR-124 functioned as tumor suppressors by targeting chemokine receptor-4 (CXCR4) and forkhead box Q1 (FOXQ1), respectively." (PMID 29581984, 2018). "More recently, research has found that high CXCL12 expression in NSCLC tumor cells correlated with high staining of these cells also for phosphorylated CXCR4." (PMID 30257500, 2018). "In contrast to free oligo‐FdU, intravenous T22‐GFP‐H6‐FdU selectively accumulates and internalizes in CXCR4+ cancer cells, triggering DNA damage and apoptosis, which leads to their selective elimination and to reduced tumor re‐initiation capacity." (PMID 30190334, 2018). "High levels of CXCL12 in organs and tissues, such as lymph nodes, lung, liver, and bone/bone marrow (BM), are thought to direct the metastasis of CXCR4-expressing tumor cells." (PMID 30191351, 2018). "C-X-C motif chemokine receptor 4 (CXCR4) was positive in 9 cases, in 7 of them very focally in a small number of tumour cells." (PMID 29976164, 2018). "SDF-1 (CXCL12)/CXCR4 signaling has been described to play a major role in tumor biology, especially in hypoxia adaptation, metastasis and migration." (PMID 30622535, 2018). "The effects of CXCR4 modulation on regulating proliferation, cell cycle and colony formation and invasion provide strong evidence for miR‐9 tumour‐suppressive effects being mediated via the inhibition of CXCR4." (PMID 29959873, 2018). "Beyond cancer stem(-like) cell induction, SDF-1/CXCR4 signaling has been demonstrated to trigger tumor invasion and metastasis as discussed in the next chapter." (PMID 30622535, 2018). "High CXCR4 expressing tumor cells have a greater invasive and metastatic potential, and CXCR4+ cells migrate following a concentration gradient of CXCL12." (PMID 30564115, 2018). "In this work, it was shown that CXCL9 and CXCL12 are co-expressed in the perivascular area of the tumor, and can form a complex enhancing CXCR4-mediated recruitment of tumor-infiltrating lymphocytes and malignant B cells." (PMID 30319638, 2018). "The C-X-C motif chemokine receptor 4 (CXCR4) is an attractive target for tumor-targeted and immuno-oncology therapeutics, with multiple mouse immunization-derived antibodies undergoing clinical trials." (PMID 29554149, 2018). "Administration of AMD3100 (CXCR4 inhibitor) increased T cell infiltration into tumor nests, and synergized with anti-PD-L1 therapy to reduce tumor growth." (PMID 30498499, 2018). "CXCR4 is overexpressed in several tumor types, where it accelerates tumor growth and invasiveness, but it can be blocked by CXCR4-specific inhibitors." (PMID 29515781, 2018). "Our model is readily suitable for evaluating the activity of anti- human CXCR4 agents in host-derived tumor microenvironment cells and/or in immuno-oncology applications using syngeneic mouse tumor-derived cell lines." (PMID 29554149, 2018). "The expression of CXCL12 mRNA was higher in rectal location (p = 0.04) with a tendency to be higher in later stages (p = 0.15), while the expression of CXCR4 was lower in tumours with a lymphatic invasion (p = 0.02), compared to their counterparts." (PMID 29887884, 2018). "In those studies, CXCL12 overexpression of CXCL12 and its receptor, CXCR4, were found in n = 6 tumor samples." (PMID 29515781, 2018).